PIF1 (PIF1 5'-to-3' DNA helicase)
Description:
DNA-dependent ATPase and 5'-3' DNA helicase required for the maintenance of both mitochondrial and nuclear genome stability. Efficiently unwinds G-quadruplex (G4) DNA structures and forked RNA-DNA hybrids. Resolves G4 structures, preventing replication pausing and double-strand breaks (DSBs) at G4 motifs. Involved in the maintenance of telomeric DNA. Inhibits telomere elongation, de novo telomere formation and telomere addition to DSBs via catalytic inhibition of telomerase. Reduces the processivity of telomerase by displacing active telomerase from DNA ends. Releases telomerase by unwinding the short telomerase RNA/telomeric DNA hybrid that is the intermediate in the telomerase reaction. Possesses an intrinsic strand annealing activity.
Synonyms: C15orf20; FLJ22692; PIF
Tractability: Small molecule: a structure with a bound ligand is known. PROTAC: ubiquitination databases record sites on it.
Gene: Protein-coding gene on chromosome 15 (64,815,629 to 64,825,677, reverse strand). Ensembl gene ENSG00000140451.
Subcellular location: Nucleus; Mitochondrion (Isoform 4)
Subcellular location (Human Protein Atlas): Nucleoplasm
Pathways (Reactome):
Cell Cycle: Telomere Extension By Telomerase
Gene Ontology:
Molecular function: 5'-3' DNA helicase activity; 5'-3' DNA/RNA helicase activity; ATP binding; ATP hydrolysis activity; magnesium ion binding; single-stranded DNA helicase activity; telomeric DNA binding; DNA helicase activity; G-quadruplex DNA binding; G-quadruplex unwinding activity; telomerase inhibitor activity
Biological process: negative regulation of telomere maintenance via telomerase; protein-DNA-RNA complex disassembly; telomere maintenance via telomerase; DNA recombination; DNA repair; telomere maintenance
Cellular component: chromosome, telomeric region; nucleoplasm; nucleus; mitochondrion
Genetic constraint (gnomAD): Loss-of-function variants: 64 observed, 55.7 expected, observed/expected ratio (o/e) 1.15, 90% interval 0.94 to 1.41. The upper end of that interval is the gene's LOEUF score, 1.41, which puts it in group 5 of 6, group 1 being the genes least tolerant of losing a copy. Missense variants: 676 observed, 659.66 expected, observed/expected ratio (o/e) 1.02, 90% interval 0.96 to 1.09. Synonymous variants: 274 observed, 272.5 expected, observed/expected ratio (o/e) 1.01, 90% interval 0.91 to 1.11.
Homologues: Orthologues: chimpanzee PIF1 (99% identical), macaque PIF1 (94% identical), dog PIF1 (90% identical), pig PIF1 (89% identical), mouse Pif1 (86% identical), rat Pif1 (86% identical), rabbit PIF1 (80% identical), guinea pig PIF1 (61% identical), zebrafish pif1 (57% identical), tropical clawed frog pif1 (56% identical), Drosophila melanogaster Pif1 (45% identical), Caenorhabditis elegans pif-1 (38% identical).
Diseases named in the same sentence as PIF1 in open-access papers:
PIF1 is named in the same sentence as 40 diseases in open-access papers, as found by Europe PMC text mining. Sharing a sentence is not in itself a finding about the gene and the disease. The quoted sentences say what the papers report.
breast carcinoma (9 papers, 2012 to 2025). "Although the human PIF1 doesn’t seem to be as essential as yeast Pif1 in the replication of G4-prone regions, its involvement in breast cancer development underlines its importance in genome maintenance." (PMID 38977862, 2024). "Regulation of Pif1 expression and activity is important, since the DNA helicase is involved in many aspects of replication and has been linked to breast cancer and obesity." (PMID 35409096, 2022). "Perhaps it is no wonder that a point mutation in the hPif1 signature motif can increase the risk of breast cancer, since Pif1 and the Pif1 signature motif play a major role in genetic stability." (PMID 35409096, 2022). "Human families with a predisposition for breast cancer carry a mutant gene encoding an L319P variant at a highly conserved location in the 21 amino acid signature motif of Pif1." (PMID 28054200, 2017). "PIF1 variant L319P was identified in three breast cancer families; importantly, this variant, which is predicted to be functionally damaging, was not identified in a large series of controls nor has it been reported in either dbSNP or the 1000 Genomes Project." (PMID 22347400, 2012). "Because this family is of Ashkenazi Jewish ancestry, we screened normal DNA from an additional 844 Ashkenazi Jewish breast cancer cases for PIF1 L319P and identified two probands who carried this allele." (PMID 22347400, 2012). "We also determined the sequence of the entire PIF1 coding sequence and 20 bp of flanking intronic sequence in normal DNA from 400 additional high-risk breast cancer probands from of European ancestry." (PMID 22347400, 2012). "Sequencing of these genes in high risk breast cancer families revealed a potential role for the helicase PIF1 in cancer predisposition." (PMID 22347400, 2012). "Our results provide a global view of nonessential genes involved in suppressing Alu-mediated recombination and implicate variation in PIF1 in breast cancer predisposition." (PMID 22347400, 2012). "To determine if additional PIF1 variants impact breast cancer risk, we determined the complete PIF1 coding sequence in a series of 400 additional high risk breast cancer probands largely of European ancestry." (PMID 22347400, 2012). "Importantly, this study demonstrated that the breast cancer-associated Pif1 mutant L319P, which resides within the Pif1 family signature motif, was defective for BIR." (PMID 34573298, 2021). "We provide genetic and functional evidence that a rare, loss of function variant in the helicase PIF1 may elevate breast cancer risk." (PMID 22347400, 2012). "PIF1 overexpression has been associated with several other cancer types including testicular, ovarian, and breast cancers, which express PIF1 at high levels, as well as cervical cancer and pancreatic cancer." (PMID 40854122, 2025). "Finally, PIF1 variant P109L, which was found in a BRCA1 mutation carrier with particularly early onset breast cancer as well as in 1 of 198 controls, is predicted to be deleterious." (PMID 22347400, 2012).
cervical cancer (5 papers, 2021 to 2025). A primary or metastatic malignant neoplasm involving the cervix. "Studies have found that PIF1 can promote cell proliferation and inhibit apoptosis in cervical cancer." (PMID 38086789, 2023). "The expression of PIF1 can promote cervical cancer cell proliferation and inhibit cell apoptosis by upregulating the expression of telomerase TERT and increasing the rate of the G2/M phase." (PMID 36685888, 2022). "Recently, several studies have pointed to the significant function of PIF1 in several different cancers, such as lung cancer, cervical cancer and neuroblastoma." (PMID 36685888, 2022). "Interestingly, 16 of 21 cancer entities analysed presented significant higher PIF1 expression level and confirmed previous data focusing on cervical cancer, non-small cell lung cancer and pancreatic cancer." (PMID 39417423, 2024).
lung carcinoma (4 papers, 2021 to 2023). "To identify novel oncogenes, we focused on 21 downregulated genes that have not been extensively investigated for potential association with lung cancer, including PIF1, GYG2, and PGM2L1." (PMID 34608398, 2021). "Here, we found that PIF1 was highly expressed in multiple cancers compared to normal tissues, including lung cancer, suggesting that PIF1 may play a crucial promoting role in lung cancer development." (PMID 38086789, 2023). "Collectively, the circNEIL3/miR-1184/PIF1 axis that mediate pyroptosis induction may be a novel, promising therapeutic strategy for the clinical treatment of lung cancer." (PMID 35190532, 2022). "In this study, we determined that WCF could significantly inhibit lung cancer cell proliferation and PIF1 was significantly downregulated after WCF treatment." (PMID 34608398, 2021). "In conclusion, the present observations indicate that WCF may inhibit lung cancer cell proliferation by promoting apoptosis via regulating the expression of PIF1." (PMID 34608398, 2021). "To further determine PIF1 function in lung cancer cell proliferation, stable PIF1 knockdown in the A549 cell line was established with a lentiviral delivery system, and we confirmed downregulation of both PIF1 protein and mRNA in this cell line." (PMID 34608398, 2021). "In this research, we found that PIF1 played an important role in promoting lung cancer cell proliferation, and it might be a critical target for WCF." (PMID 34608398, 2021). "Previous studies suggested that the knockdown of PIF1 inhibited the growth of human NSCLC cells and promoted cell apoptosis and could serve as a potential therapeutic target for treating lung cancer." (PMID 36685888, 2022). "In summary, PIF1 may be a critical gene that regulates lung cancer cell proliferation and apoptosis, which may serve as a potential target of WCF in treating lung cancer." (PMID 34608398, 2021). "Currently, the role of PIF1 in lung cancer cells is still not reported." (PMID 34608398, 2021).
neuroblastoma (4 papers, 2021 to 2025). Neuroblastoma (NB) is the most common solid, extracranial childhood tumor. "Consistently, increased PIF1 expression has already been shown to direct worse outcome in patients suffering from neuroblastoma and advanced stage in KIRC." (PMID 39417423, 2024). "High PIF1 expression was additionally found to be correlated with reduced survival outcomes in neuroblastoma patients, indicating that the role of PIF1 in G4 biology may be relevant in other cancers." (PMID 40854122, 2025). "It had been reported that PIF1 depletion could reduce the survival of neuroblastoma cells by triggering apoptosis, which was dependent on the activity of caspase-3, while nonmalignant cells were not affected by PIF1 depletion." (PMID 34608398, 2021).
lung adenocarcinoma (3 papers, 2022 to 2024). A carcinoma that arises from the lung and is characterized by the presence of malignant glandular epithelial cells. "Researchers discovered that circNEIL3 (hsa_circ_0001460) might mediate radiation-induced pyroptosis by sponging miR-1184 to upregulate PIF1 expression, providing a novel treatment option for lung adenocarcinoma therapy." (PMID 38177102, 2024). "In addition, circNEIL3 contributes to pyroptosis and activates AIM2 inflammasome by sponging miR-1184 to release the suppressed PIF1 in lung adenocarcinoma." (PMID 38177102, 2024). "Other telomere maintenance genes showed limited evidence of colocalisation with lung adenocarcinoma (i.e. TERF1 and PIF1)." (PMID 37079368, 2023).
glioblastoma (2 papers, 2022 to 2025). The most malignant astrocytic tumor (WHO grade IV). "The RUNX1-BIRC5/PIF1-p21 pathway appears to reflect refractory characteristics of glioblastoma and thus holds promise as a therapeutic target." (PMID 36085167, 2022). "Here, we show that RUNX1 downregulates p21 by enhancing expressions of BIRC5 and PIF1, conferring anti-apoptotic properties on glioblastoma." (PMID 36085167, 2022). "The most downregulated gene in both TMZ and TMZ + TO‐treated glioblastoma cells was PIF1." (PMID 39680504, 2025).
adenoma (1 paper, 2025). A neoplasm arising from the epithelium. "The study identified mutations in senescence-associated genes, namely, ATM, PIF1, TELO2, XAF1, and RBL1, in five of twenty subjects with multiple adenomas, indicating germline loss-of-function variants in genes that regulate senescence pathways with the development of serrated adenomas." (PMID 40699620, 2025).
bladder urothelial carcinoma (1 paper, 2022). "The results from the database showed that PIF1 was significantly upregulated in 21 out of all 33 cancer types compared with normal tissues, such as testicular germ cell tumor (TGCT), bladder urothelial carcinoma (BLCA), cervical squamous cell carcinoma and endocervical adenocarcinoma (CESC)." (PMID 36685888, 2022).
clear cell renal cell carcinoma (1 paper, 2022). "However, the relationship between clear cell renal cell carcinoma (ccRCC) and PIF1 remains unclear." (PMID 36685888, 2022).
diabetes (1 paper, 2019). "Diabetes, obesity, and cholesterol concentrations in serum from Western diet-fed, WT and PIF1 KO female mice." (PMID 31136580, 2019). "The apparent protection against insulin resistance in PIF1 KO female mice prompted us to examine specific serum factors that are commonly dysregulated during diabetes and obesity." (PMID 31136580, 2019).
familial breast cancer (1 paper, 2020). "The human PIF1 helicase (hPIF1) is associated with familial breast cancer, and in these families a point mutation is found in the Pif1-encoding gene." (PMID 33045725, 2020).
Fanconi anemia (1 paper, 2024). Fanconi anemia (FA) is a hereditary DNA repair disorder characterized by progressive pancytopenia with bone marrow failure, variable congenital malformations and predisposition to develop hematological or solid tumors. "Factors that normally mediate replication fork stability, including members of the Fanconi anemia gene family and the helicases PIF1 and RECQL5, showed reduced accumulation at replication forks in the absence of RNF4." (PMID 38530355, 2024).
Hepatic steatosis (1 paper, 2019). Steatosis is a term used to denote lipid accumulation within hepatocytes. "Overall, these results showed that WD-fed PIF1 KO female mice developed mild hepatic steatosis with modest gene expression changes in relevant metabolic pathways." (PMID 31136580, 2019). "WD-fed PIF1 KO females developed mild hepatic steatosis and associated changes in liver gene expression that were absent in weight-matched, WD-fed female controls, linking hepatic steatosis to Pif1 ablation rather than increased body weight." (PMID 31136580, 2019). "PIF1 KO female mice uniformly exhibited mild hepatic steatosis compared to WT mice." (PMID 31136580, 2019). "Similarly, the absence of changes in fasting blood glucose concentrations and glucose tolerance despite increased hepatic steatosis in WD-fed PIF1 KO females was surprising given the strong, positive association between liver fat, hyperglycemia and hepatic insulin resistance." (PMID 31136580, 2019). "WD-fed PIF1 KO females developed a mild hepatic steatosis that appeared independent of weight gain, and without severe gene expression derangement." (PMID 31136580, 2019).
medulloblastoma (1 paper, 2025). A malignant, invasive embryonal neoplasm arising from the cerebellum. "In this study, we highlight the intrinsic vulnerability of Brca2Δex3-4 GCPs to replication stalling at G-quadruplex-rich loci that may lead to the mutations that drive medulloblastoma and the role of the PIF1 helicase in promoting tumor maintenance." (PMID 40854122, 2025). "Targeting PIF1 may represent a therapeutic strategy for BRCA2-deficient medulloblastomas." (PMID 40854122, 2025). "Pif1 helicase, which resolves G4s during replication, was highly upregulated in tumors, and Pif1 knockout in primary medulloblastoma tumor cells resulted in increased genome instability upon pyridostatin treatment." (PMID 40854122, 2025).
Obesity (1 paper, 2019). Accumulation of substantial excess body fat. "Surprisingly, PIF1 KO female mice were protected against the glucose intolerance and inflammation that are typically associated with obesity." (PMID 31136580, 2019). "By extension, we speculate that a PIF1 deficiency in humans might only cause obesity on Western diets." (PMID 31136580, 2019). "The dissociation between obesity and metabolic dysfunction in WD-fed PIF1 KO female mice is reminiscent of metabolically healthy obesity." (PMID 31136580, 2019). "This suggested that Pif1 could play a role in the pathogenesis of obesity, although it remains unclear how Pif1 contributes to body weight maintenance." (PMID 31136580, 2019). "To determine whether differences in steatosis were due to obesity, we compared a weight-matched subset of animals (3 WT and 4 PIF1 KO) and found steatosis only in the PIF1 KO animals." (PMID 31136580, 2019).
ovarian carcinoma (1 paper, 2024). A malignant neoplasm originating from the surface ovarian epithelium. "We also used BRCA1-deficient ovarian cancer cell line UWB1 75,76 and showed that acquired Olaparib resistance of UWB1 cells upon 53BP1 depletion can be reverted by inhibiting PIF1." (PMID 39314326, 2024).
pancreatic adenocarcinoma (1 paper, 2022). "Furthermore, PIF1 expression was upregulated in other cancers of various organs, including stomach adenocarcinoma (STAD), sarcoma (SARC), pancreatic adenocarcinoma (PAAD), and others." (PMID 36685888, 2022).
prostate adenocarcinoma (1 paper, 2022). "However, decreased PIF1 expression was found in 5 of 33 cancer types, including adrenocortical carcinoma (ACC), kidney chromophobe (KICH), prostate adenocarcinoma (PRAD) and others." (PMID 36685888, 2022).